IL1B (interleukin 1 beta)
Diseases named in the same sentence as IL1B in open-access papers (continued):
Sharing a sentence is not in itself a finding about the gene and the disease.
tumor (continued). "Given that TNF-α and IL-1β promoted the expression of OPN in tumor cells, we wondered whether TNF-α and IL-1β promote the expression of OPN in adjacent macrophages." (PMID 39726047, 2024). "In GCV control mice, PD-L1 inhibition had no impact on mRNA levels of Cd206, Cd38, Cd80 and Il-1β, highlighting the relevance of tumour biology and systemic impact of cancer on the side effects of PD-L1 inhibitors." (PMID 39834851, 2024). "Measurement of tumor volume after 30 days showed that compared to the control group, the subcutaneous tumor volume significantly decreased in the MLT group, si-NLRP3 group, and IL-1β Ab group, while it significantly increased in the oe-NLRP3 group and IL-18 Ab group." (PMID 39230586, 2024). "Sch B treatment also inhibits IL-1β-induced EMT expression of TNBC cells, which may contribute to the anti-tumor response." (PMID 38254674, 2024). "However, the presence of pro-inflammatory cytokines such ad IL-17, IL-6, IL-1β, and TNF-α leads to the chronic activation of inflammatory signals that not only suppresses adaptive immune responses, but also induce tumor growth." (PMID 39767682, 2024). "Our findings continued to indicate a higher proportion of the IL1B+ cDC2 population in the tumor tissues of treatment-naïve patients, but not in their normal tissues." (PMID 38948071, 2024). "Moreover, we examined the roles of several growth factors and inflammatory cytokines in PDL1 expression HNSCC cells, such as epidermal growth factor (EGF), LPS, IL-6, IL-1β, and TNF-α, commonly in tumor microenvironment." (PMID 38945975, 2024). "Key differentially expressed genes included PTGS2 (pro/antitumor), FOSL1, TNFRSF9, IL1B, DIO2, and PHLDA1 (antitumor), along with under-expressed genes with pro-tumor effects that may inhibit proliferation." (PMID 39409923, 2024). "Indeed, p65 deficiency enhances CD8+T cells proliferation and increases levels of IFN-γ, TNF-α and IL-1β, which lead to a decreased GBM tumor growth." (PMID 38397187, 2024). "In addition, MMP-9 produced by tumor cells drives malignant progression and metastasis and high levels of inflammatory cytokines such as TNF-α, IL-1β, Il-6, and IL-8 present in CM can also significantly increase MMP-9 expression." (PMID 39072314, 2024). "The TAM model in the simulated tumor microenvironment was treated with dCP1 and dCPP, respectively, and it was found that glycopeptide can better reduce Mrc1 in M2-like TAM and increase the relative expression levels of IL-1β and IL-6 mRNA." (PMID 38743074, 2024). "As expected, caspase-1 did not affect IL1β gene expression, and because of the absence of paracrine stromal-tumor cell interaction, KBP cells grown in monolayer produced minimal IL1β9." (PMID 39353903, 2024). "Consequently, the decreased expression of ZFP36L2 leads to the increased secretion of cytokines, such as IL1β, MMP-9, and TNF-α, by T cells, thereby promoting tumor apoptosis." (PMID 39767767, 2024). "Finally, analysis of common SASP markers in tumor tissues demonstrated that ADR markedly stimulated the expression of IL-6, IL-1β, and IL-1α, while TC significantly inhibited their expressions." (PMID 39364046, 2024). "Increase the expression of NO, IL-1β, IL-6 and TNF-α in tumor-bearing mice." (PMID 39560523, 2024). "Preclinical studies revealed that mice lacking IL-1β have a slower tumor growth and a stronger immune response than wild-type mice." (PMID 38103126, 2024). "Mcp-1 and IL-1β expression was not affected by tumor factors from either cachectic or non-cachectic patients." (PMID 38339292, 2024).
tumor (continued). "Besides, M1 macrophages can facilitate tumor neoangiogenesis while suppressing anti-tumor immunity by up-regulating pro-inflammatory molecule expression (iNOS, TNF-α, and IL-1β), thus exhibiting anti-tumor activity." (PMID 37735297, 2024). "Hence, we correlated the expression level of the tumor-upregulated gene signature, comprising HAS2, MMP9, CXCL8, CXCL11, IL1B, and IL6, with the ratio of infiltrating M1 macrophages." (PMID 38329386, 2024). "Additionally, they observed that NT157 not only reduced tumor burden but also suppressed the expression of various pro-tumorigenic chemokines (e.g. CCL2) and cytokines (e.g. IFN-γ and IL-1β), which are critical for TAM recruitment." (PMID 38229160, 2024). "•Can IL-1B be targeted to prevent bone metastasis without adversely affecting tumour development in soft tissues?" (PMID 38800348, 2024). "In this regard, LPS and ATP were used for canonical NLRP3 inflammasome activation and pyroptosis induction, while MCC950 was used for specific inhibition of NLRP3 and IL-1β release, after which PTX was added to suppress the proliferation of tumor cells and programmed cell death initiation." (PMID 39433537, 2024). "IL-1β contributes to TAN recruitment by upregulating endothelial cell adhesion molecules, enhancing the adhesion of TANs to the endothelium, and facilitating their subsequent extravasation into the tumor tissue." (PMID 38360737, 2024). "Interestingly, we also observed that OPN expression in tumor cells was also increased when they were treated with TNF-α or IL-1β, and a dual effect was shown when they were treated with both TNF-α and IL-1β." (PMID 39726047, 2024). "In agreement with the upregulation of MHC, we also observed a strong enrichment in interferon signaling for effective tumor-suppressing treatments, particularly for NT GSDMD + IL-12, as well as for ineffective NT GSDMD + IL-1β + IL-18 treatment, although not necessarily with the same genes." (PMID 39737979, 2024). "Based on our observations, we speculate that IL-1β, following inflammasome activation and GSDMD pore formation, attracts myeloid cells to the tumor and promotes CRC development by signaling to cancer cells, myeloid cells, as well as tumor-infiltrating T cells." (PMID 38898209, 2024). "In fact, the release of the main effectors of pyroptosis (IL‐1β, IL‐18 and HMGB1) breaks down the ‘cold’ tumour properties and increases the infiltration of anti‐tumour immune cells in the TME, while at the same time decreasing the infiltration of suppressor immune cells." (PMID 38652105, 2024). "Additionally, tumor cells activate TAMs through the TLR4/TRIF/NF-κB signaling pathway and upregulate HIF1α-mediated IL-1β production to stimulate EMT of tumor cells." (PMID 38957393, 2024). "Increasing research indicates that adipokines (such as leptin, resistin, visfatin, etc.)and inflammatory factors (such as IL-1β, IL-6, chemokines, FABP4, etc.)secreted by BMA can also regulate angiogenesis, indirectly facilitating the progression of tumor bone metastasis." (PMID 38571500, 2024). "Therefore, we used the tumor IMmune Estimation Resource (TIMER) Web Server to investigate FN1, CXCL8, IL1β, and ITIH4's function in the Comprehensive Analysis of tumor-infiltrating Immune Cells." (PMID 38637796, 2024). "Notably, tumor immune‐related cytokines, including tumor necrosis factor (TNF)‐α, IL‐1β, IL‐2, IL‐6, IL‐17, CD4+/CD8+, IFN‐α, and IFN‐γ, were determined." (PMID 36951443, 2023). "Furthermore, SPP1+ TAMs promote mCAF activation by secreting IL-1β or TGF-β1, which facilitates co-mediation of ECM remodeling by SPP1+ TAMs and mCAFs to form a pro-tumor fiber microenvironment that impedes lymphocyte infiltration." (PMID 37853464, 2023). "This observed increase may possibly indicate that MPs in group D could result in the overexpression of IL-1β in the GIFT brain, which may be a sign of tumor progression in the brain." (PMID 37998029, 2023).
tumor (continued). "Before compounds such as IL-1β neutralizing antibodies and IL-18 binding protein can be clinically applied, a deeper understanding of the biological mechanisms of NLRP3 activation, IL-18R- and IL-1R signaling, in regards to tumor progression is needed." (PMID 36766797, 2023). "Tumor CM stimulated the production of IL-1β which was significantly inhibited with RNAase H, and not RNAase A. Interestingly, only a slight reduction was observed with DNAase treatment." (PMID 37449203, 2023). "In addition, the IL‐1b antibody and MCC950 significantly increased the percentage of CD8+ T cells in tumor‐bearing mice." (PMID 38116060, 2023). "They home into the tumor site, following secretion of soluble factors, such as IL-6, IL-1β, and/or transforming growth factor-β1 (TGF-β1) by tumor cells, as well as the stromal cell-derived factor1α (SDF-1α) by stromal cells that promote paracrine signaling in tumor cells." (PMID 37175439, 2023). "Especially, IL-1β may induce IFN-γ production, while TNF-α and IFN-γ can kill tumor cells and inhibit tumor growth directly." (PMID 37951973, 2023). "While data here clearly demonstrate that maximum human NOS2 expression is induced by IFNγ, IL1β, and TNFα, identical to that in murine tumor cells, human macrophages do not activate NOS2 with IFNγ or LPS." (PMID 37169743, 2023). "The upregulation of TNF-α, IL1β, and Bcl-2 genes suggests that the CLT was able to initiate an inflammatory response to combat the tumor, while the downregulation of the Bax and Beclin1 genes indicates that the CLT was able to reduce the risk of apoptosis in the liver." (PMID 37160480, 2023). "The expression level of IL-1β correlated with the size of the metastatic lesion, being absent in tumor-free brain areas and more intense in the vicinity of large tumors in comparison to smaller ones." (PMID 37749707, 2023). "IL-1β can induce VEGF expression, which increases tumor aggressiveness." (PMID 37461742, 2023). "The IHC grade of IL-1β in IL-1β-positive tissues was significantly higher than that in IL-1β-negative tumor tissues (P < 0.001)." (PMID 37106440, 2023). "In other studies, tumour-derived NLRP3 increases the expression and secretion of IL-1β by MDSCs." (PMID 36161514, 2023). "Additionally, it also controls the inflammatory response within the tumor microenvironment by reducing the expression levels of TNF-α, IL-1β, and IL-6." (PMID 37894468, 2023). "Additionally, IL-1β and hepatoma-derived growth factor (HDGF) trigger MSCs to secrete tumor-promoting cytokines that support tumor progression." (PMID 37626931, 2023). "Moreover, pro-inflammatory mediators such as IFNγ, IL-1β, and IL-6 also induce EMT-TFs, leading to chronic inflammation in the tumor microenvironment, immune escape, and the acquisition of EMT-like features in tumor cells." (PMID 37370762, 2023). "In addition, it reduced IL-1β, IL-4, IL-6, IL-10, and IL-13 levels, down-regulated PI3K, ERK1/2, and up-regulated EGFR levels, improving the anti-tumor effects of the tumor suppressor microenvironment." (PMID 37397393, 2023). "We established a subcutaneous tumor mouse model using Hepa1‐6 cells and observed that administration of oxaliplatin had a pronounced effect on inhibiting tumor growth and led to notable upregulation of NLRP3 and IL‐1β." (PMID 38116060, 2023). "Similarly, the up-released IL1β by TAMs activates the p38 MAPK signaling pathway and expression of CCL2 by tumor cells." (PMID 37012233, 2023). "Additionally, IL-19 involved the role of MMP2, IL-6, MMP9, IL-1β, CXCR4, fibronectin, and TGF- β for tumor development." (PMID 37675062, 2023). "Similarly, iNos, IL-1b, and TNFα expression was increased in responder-derived TES-treated macrophages, indicating the enhanced anti-tumor activity of macrophages for inducing T cell immunity." (PMID 36707872, 2023).
tumor (continued). "Mutant KRAS-IL-1β addiction is mediated via secretion of the glycoprotein versican (VCAN) by tumor cells, which inhibits the NF-κΒ kinase (IKK) β in macrophages, resulting in IL-1β release into the tumor microenvironment." (PMID 36980752, 2023). "Although, as previously reported by others, IL-1β neutralization did not affect spontaneous tumor formation in KrasG12D mice, it almost completely abolished the tumor-promoting effect of HDM." (PMID 36670473, 2023). "Notably, antitumor cytokines, such as IL‐1β, IFN‐γ, and IL‐12, were upregulated ≈15‐fold, whereas neutrophil‐related tumor immune checkpoints, such as SIRPα and PDL1, and protumor markers, such as VEGF and TGFβ‐R1, were downregulated significantly." (PMID 37565362, 2023). "Two days after the inoculation of the tumor cells, no IL-1β was observed in the frontal, temporal and parietal cortical regions of the mice." (PMID 37749707, 2023). "IL-1β also increases the expression of matrix metalloproteinases (MMPs), which degrade extracellular matrix (ECM) proteins, facilitating the migration and invasion of tumor cells into surrounding tissues." (PMID 37511306, 2023). "During the screening of composite cells, it was discovered that both IL-1β and TGF-β could stimulate the production of IFN-γ in composite cells for tumor suppression." (PMID 37680632, 2023). "Taken together, these data illustrate that IL‐1β released when Mφ communicates with tumor cells induces immunosuppression without directly inhibiting functional cytokines expression of T cells." (PMID 37009412, 2023). "The TME of tumor cells treated with the combination of anti-IL-1β and anti-PD-1 therapies showed a statistically higher percentage of CD8+ T cells, indicating a reversal of the immunosuppressive effects of IL-1β." (PMID 37511306, 2023). "In addition, we found that with the evolution of tumor cell status, the expression levels of FLT3LG, GALNT10, IL1B, and IMPDH1 remained stable while ISG20 gradually increased." (PMID 36816023, 2023). "In addition, another study showed that HMGB1 synergistically induced IL-1b release from dc with ATP and that HMGB1-specific antibodies eliminated the ability of dc to contact dying tumor cells to produce IL-1b." (PMID 37305384, 2023). "Moreover, the expression of Ifn-γ and Il-1β in tumor samples of anti-PD-1 responder mice, might suggest the infiltration by other antitumor immune system cells.Therefore, taken together these data we provide a potential mechanistic explanation for the enhanced tumor response observed." (PMID 37841258, 2023). "Compared with the healthy tissues, the tumor tissues exhibited significantly elevated concentrations of arecoline and arecoline N-oxide and expression levels of a somatic protein (NOTCH1) and proinflammatory markers (IL-1β and IL-17)." (PMID 37190117, 2023). "In the tumor ecosystem, fibroblasts convert to CAFs via TGF-β and IL-1β signaling pathways." (PMID 37024932, 2023). "The differences in Il-10 and Il-1β expression changes between recombinant CCL21 treatment and upon CCL21 neutralization from GBM CM suggests that CCL21 cooperates with other soluble factors secreted by tumor cells to induce TAM polarization in the TME." (PMID 37314567, 2023). "Given the predominance of IL-10, IL-6, IL-1β and VEGF in MDSC secreted supernatant and increased expression of corresponding receptors on tumor cells following co-culture with MDSC and MDSC-supernatant, next we tried to validate the role of individual cytokine in induction of MDR." (PMID 38304256, 2023). "In addition, YFJP significantly reduced the expression of inflammatory and immunosuppressive cytokines, including IL-1β, IL-6 and IL-10, while increased the expression of cellular effectors TNF-α and IFN-γ in serum and tumor tissues." (PMID 37355637, 2023). "Moreover, IL-37 reduces tumor promoting cytokines including IL-6, IL-1β and TNF-α produced by both tumor cells and immune cells." (PMID 37928545, 2023).
tumor (continued). "For example, the cytokine, interleukin-1beta (IL1β) was specifically shown to be induced in female post tumor growth and was not expressed in males." (PMID 37573456, 2023). "Regarding cytokine secretion, piperine reduced IL-1β secretion in HeLa and SiHa cells, did not produce significant changes compared with the control in CaSki cells, and increased secretion in non-tumor cells (HaCaT)." (PMID 36678600, 2023). "In addition, genes such as IGF143 have been associated with increased CRC tumor growth and aggressiveness, suggesting that the IL1R1+ iCAF subtype may possess other potential pro-tumorigenic effects in addition to its elevated IL1R1 expression and IL-1β signaling." (PMID 37460545, 2023). "Cisplatin induces an increase in CCL20 and IL-1β in tumor cells within a cold tumor model, both of which activate ILC3s to release the chemokine CXCL10, attracting CD4 T and CD8 T lymphocytes to infiltrate tumor tissue and then exert anti-tumor effects." (PMID 37122757, 2023). "Similarly, pharmacological inhibition of IL-1β or IL-1R1 locally decreases intratumoral TAM content and prolongs survival of tumor-bearing mice." (PMID 37733448, 2023). "Concomitantly, a sandwich ELIZA for pro-inflammatory cytokines (TNF-α, IL-1β, IL-6 and IL-12) revealed a dose-dependent reduction in levels of pro-inflammatory cytokines (p<0.05 and p<0.001) of ART-treated tumor-bearing mice compared to the untreated tumor-bearing mice." (PMID 38144525, 2023). "At the cellular level, IL-1β is known to stimulate angiogenesis in the tumor microenvironment (TME), and to induce the production of IL-6 and IL-17A, which are well-established mediators of tumor growth." (PMID 36670473, 2023). "This loop further interconnected IL1β with the expression of IL1R1 in luminal cancer cells MCF7 and SKBR3, fostering functional crosstalk between the tumor microenvironment and intracavitary breast cancer cells, consequently promoting tumor metastasis." (PMID 38001753, 2023). "In the tumor grading analysis, IL-1β and TNF-α did not present significantly different values in patients with G1, G2, and G3 tumors; therefore, these cytokines cannot be taken into account in the prediction of grading in patients diagnosed with CRC." (PMID 38137862, 2023). "‐LPMs characterized in tumor‐bearing mice as F4/80high GATA6+ cells that proliferated during tumor progression.‐No expression of prototypical protumoral genes (IL10, TGFB and Retnla), but of proinflammatory genes (IL6, TNFA and IL1B)." (PMID 36658699, 2023). "Moreover, myeloid cells promote tumor growth by secretion of pro-inflammatory cytokines such as IL1b, IL6 and IL15, which have been shown to promote inflammation and tumor growth." (PMID 36761972, 2023). "Although the use of animal models could provide data on the interaction between tumor and immune cells, the primary objective of this work was to determine the endogenous baseline NLRP3 inflammasome levels and IL‐1β secretion of CM and UM." (PMID 36707938, 2023). "The increase in the number of macrophages in the tumour microenvironment (TME) promoted tumour cell epithelial-mesenchymal transition (EMT) and significantly increased CXCL1 levels in the TME partly through NF-κB/IL-1β activation." (PMID 37037815, 2023). "In line with this, treatment of mice bearing the Arf1‐ablated tumor cells with anti‐IFNAR1 and anti‐IL‐1β antibodies had markedly reduced frequency of the TNF+IFNg+PD1+CD8+ T cells in tumors in comparison with those in tumors treated with the isotype control antibody." (PMID 37786300, 2023). "In close correlation with the development of inflammatory reactions and TNBC is the activation of the NLRP3 inflammasome complex, with IL-1β and IL-18 being the two major cytokines activated by NLRP3 inflammasome, which promote tumor cell proliferation and invasion." (PMID 36834660, 2023).